CCN3 (cellular communication network factor 3)
Diseases named in the same sentence as CCN3 in open-access papers (continued):
Sharing a sentence is not in itself a finding about the gene and the disease.
Parkinsonism (1 paper, 2020). Characteristic neurologic anomaly resulting from degeneration of dopamine-generating cells in the substantia nigra, a region of the midbrain, characterized clinically by shaking, rigidity, slowness of movement and difficulty with walking and gait. "Here we present evidence that a rare homozygous mutation in CCN3 found in a family in rural Pakistan may be a novel cause of parkinsonism." (PMID 32499748, 2020). "Nevertheless, this study has identified a strong interesting parkinsonism candidate, CCN3, highlighting the utility of screening isolated affected families for identification of putative disease-causing genes." (PMID 32499748, 2020).
relapsing-remitting MS (1 paper, 2020). "Plasma CCN3 levels were comparable between collective MS cohorts and controls but were significantly higher in progressive versus relapsing-remitting MS and between patients on interferon-β versus natalizumab." (PMID 33222687, 2020).
sarcoma (1 paper, 2018). A usually aggressive malignant neoplasm of the soft tissue or bone. "In transfected CCN3-negative Edwing’s sarcoma cell line with CCN3, the cell proliferation was reduced but migration and invasion was increased." (PMID 28575190, 2018).
schizophrenia (1 paper, 2019). A major psychotic disorder characterized by abnormalities in the perception or expression of reality. "Thirdly, CCN3 (NOV) is functionally related to genes in which mutations are disproportionately highly observed in schizophrenia cases relative to controls." (PMID 31849729, 2019). "In a recent comparison of global gene expression in prefrontal parvalbumin cells from individuals with schizophrenia versus healthy controls, more than 800 transcripts were identified as being differentially expressed, with CCN3 being one of the top hits (>40% change in expression)." (PMID 31849729, 2019).
Thrombocytopenia (1 paper, 2023). A reduction in the number of circulating thrombocytes. "In our study, we found that serum CCN3 levels were significantly higher in SLE patients compared to normal subjects and were associated with thrombocytopenia." (PMID 37749230, 2023).
tubulointerstitial nephritis (1 paper, 2015). "In agreement with our experimental data, NOV/CCN3 expression was highly increased in biopsies of patients with tubulointerstitial nephritis." (PMID 26367310, 2015).
type 1 diabetes mellitus (1 paper, 2021). A chronic condition characterized by minimal or absent production of insulin by the pancreas. "However, most studies have focused on the association between CCN3 and T2MD, while few have reported type 1 diabetes mellitus (T1DM)." (PMID 34393649, 2021).
uveal melanoma (1 paper, 2021). A melanoma derived from melanocytes of the uveal tract. "When we further evaluated the association between CCN3 expression and prognosis in pan-cancer, we found that high CCN3 expression was associated with shorter OS in seven types of cancer (ACC, BLCA, GBM, LAML, MESO, STAD, and uveal melanoma) and longer OS in two types of cancer (CHOL and KIRC)." (PMID 33833779, 2021).
tumor (46 papers, 2004 to 2025). "Amino terminus-truncated CCN3 variants, identified from Hela and other tumor cells, are localized in the nucleus, which is presumably associated with oncogenicity of the CCN3 variants." (PMID 35476850, 2022). "In the present study, we confirmed that high OPN expression is significantly correlated with tumor dimension and vascular thrombosis and that it has a positive association with CCN3." (PMID 29061995, 2017). "Further studies in our group will focus on exploring an association between HCC with overexpressed CCN3 and the number of tumor clusters in the circulation to find means for tumor inhibition via anticoagulants in tumor metastasis." (PMID 29061995, 2017). "Other studies have otherwise indicated that high CCN3 expression is associated with increased proliferation rates or tumor promoting potential in many cancer types." (PMID 24551846, 2014). "Here, we provide the first evidence that PCa-derived CCN3 recruits macrophages and contributes to tumor-associated angiogenesis in human PCa." (PMID 24721786, 2014). "Because CCN3 was the first member of the CCN family to be associated with tumour development, it is the most studied CCN protein with regard to tumour typing and prognosis." (PMID 18789696, 2008). "Furthermore, Cox regression analysis revealed a significant association of CCN3-high expression in tumor tissue with tumor dimension (p = 0.013), vascular invasion (p = 0.023), and tumor encapsulation (p = 0.014) of HCC." (PMID 31805888, 2019). "Furthermore, CCN3 expression was positively correlated with Twist expression in PCa specimens, suggesting that CCN3 is linked with Twist expression and tumor metastasis in PCa." (PMID 29088803, 2017). "In addition, high expression of CCN2 relative to low CCN3 levels was associated with enhanced tumor formation, angiogenesis and the ability to form bone metastases." (PMID 22427255, 2012). "Alternatively, the well-documented increased production of proteases by tumor cells might also lead to large quantities of the truncated CCN3 variant that are detected in the conditioned medium of CCN3-expressing cells and consecutive increased internalization of these variants." (PMID 16504021, 2006). "We identified that CCN3 knockdown diminished cancer stem cell formation, metastasis, and tumor growth in vitro and in vivo." (PMID 36737605, 2023). "Based on these findings, we concluded that the expression of CCN3 can induce EGFR-dependent tumor progression as well as EGFR activation." (PMID 36737605, 2023). "In accordance with this expectation, subsequent studies revealed the antiproliferative effect of CCN3 on chondrocytes, osteoblasts, vascular smooth muscle cells and tumor cells." (PMID 35682564, 2022). "CCN1 and CCN3 have been shown to exhibit a dual nature of tumor inhibition and tumor suppression to some extent in quiet recent time." (PMID 34940056, 2021). "The beneficial remodeling of the tumor stroma supports the potential value of these CCN3-derived peptides for targeting pathways regulated by CCN2 in PDAC." (PMID 32294968, 2020). "In a murine orthotopic PDAC model, the two peptides, administered as monotherapy at low doses (approximating physiological levels of CCN3), had tumor inhibitory activity that increased with the dose." (PMID 32294968, 2020). "CCN3 was readily detected NCI-H295R cells, a tumor line that expresses CCN3, indicating the validity of our method of detecting CCN3 protein." (PMID 31170244, 2019). "Immunofluorescence and immunoblotting assays revealed a higher expression of CCN3 in HCC tumor tissue samples than in non-tumor tissue samples." (PMID 29061995, 2017). "The common features of EMT and stem cell plasticity implicate the crucial role played by CCN3 in tumor progression." (PMID 29088803, 2017). "IHC staining confirmed a positive correlation between the expression of CCN3, Twist, and tumor stage in PCa tissue." (PMID 29088803, 2017).
tumor (continued). "The data from our orthotopic model show that the knockdown of CCN3 expression dramatically abolishes tumor growth and metastasis, especially bone metastasis." (PMID 29088803, 2017). "Our orthotopic tumor model provides strong support for the contention that CCN3 is responsible for bone-tropic PCa metastasis." (PMID 29088803, 2017). "We observed an increased CCN3 expression level in 54.16% (26/48) of the HCC samples compared to non-tumor liver tissue samples." (PMID 29061995, 2017). "In contrast, the overexpression of CCN3 through lentiviral infection of Hep3B cells in mice led to enhanced subcutaneous tumor growth." (PMID 29061995, 2017). "In summary, these results showed that tumor-secreted CCN3 increased macrophage migration and adhesion to PCa cells." (PMID 24721786, 2014). "Recent studies have shown a correlation between CCN3 expression and tumor progression in many cancers, and CCN3 has been proposed to increase the migration of PCa cells by influencing ICAM-1 expression." (PMID 24721786, 2014). "These in vivo results confirm that PCa-secreted CCN3 can regulate macrophage M2 polarization, macrophage-promoted angiogenesis in a tumor environment." (PMID 24721786, 2014). "Knockdown of CCN3 expression markedly inhibited cell migration in vitro and tumor growth in bone and bone metastasis in vivo." (PMID 24551846, 2014). "In conclusion, these results indicate that PCa-derived CCN3 regulates TAM function to promote angiogenesis in the tumor environment." (PMID 24721786, 2014). "Only a fraction (5/44) of samples displayed higher levels of CCN3 in the tumor compared to normal breast tissue." (PMID 22427255, 2012). "In a different cohort of 122 human breast tumors and 32 normal breast tissues, lower CCN3 mRNA and protein levels were observed in tumor tissues when compared to normal samples." (PMID 22427255, 2012). "• Known as CCN3, a member of the secreting insulin like growth factor binding protein family with antiprolifereative effects on tumor cells." (PMID 22111699, 2011). "In musculoskeletal tumours, including rhabdomyosarcoma, and cartilage tumours, CCN3 expression correlates positively with tumour differentiation." (PMID 18789696, 2008). "Studies performed on tumor cells have allowed to pinpoint several aspects of CCN3 biology that are altered upon initiation or during progression of cancers." (PMID 16504021, 2006). "It was also shown in two other collaborative studies using either constitutive or inducible expression vectors, that the ectopic production of ccn3 induced a dramatic reduction of cell proliferation in all the tumor cells tested." (PMID 16504021, 2006). "The blastemal cells which were positive for ccn3 also express high levels of viral sequences and give rise to the tumor cells that develop later." (PMID 16504021, 2006). "In support for a role of CCN3 in the regulation of transcription, we had previously reported that the expression of an amino truncated CCN3 protein identified in tumor cells was inducing chicken embryo fibroblast proliferation and transformation." (PMID 16895594, 2006). "Many members of this family, such as periostin, osteopontin (SPP1), or the CNN (Cyr61, CCN2, CCN3) family of proteins, have been shown to regulate key aspects of tumor biology, including proliferation, invasion, matrix remodeling, and dissemination to pre-metastatic niches in distant organs." (PMID 37240298, 2023). "Interestingly, however, in this report, the expression level of CCN3 was decreased in tumor tissues compared to normal tissues." (PMID 36737605, 2023). "The results showed that the tumor growth was significantly reduced by CCN3 knockdown." (PMID 36737605, 2023). "However, in the case of CCN3, the matricellular protein shows different glycosylation patterns depending on the tumor progression status, and the function varies according to the glycosylation pattern." (PMID 36737605, 2023).
tumor (continued). "Since it was confirmed that the activity of EGFR can be enhanced by GPNMB, we further investigated whether CCN3-induced metastasis and tumor progression were mediated by GPNMB-induced mechanisms." (PMID 36737605, 2023). "CCN3 has been reported to act as a suppressor of proliferative activity in tumor cell lines." (PMID 36499638, 2022). "However, the role of CCN3 in the tumor is exceedingly complex, because the functions of CCN3 have been shown to differ in various types of malignancies." (PMID 34393649, 2021). "By contrast, CCN3 acts as a tumor promoter in liver, pancreatic, and prostate cancer." (PMID 33833779, 2021). "CCN3 has antiproliferative activities in several tumor cell lines." (PMID 33066270, 2020). "In addition, immunohistochemical staining revealed the proportion of CCN3 expression was significantly up-regulated in oxaliplatin-resistant HCC subcutaneous tumor tissue." (PMID 31805888, 2019). "The prognostic value of CCN3 differs according to type of tumor." (PMID 29088803, 2017). "Recent studies have shown a correlation between CCN3 expression and tumor progression in many cancers, and research suggests that CCN3 may increase the migration of PCa cells by influencing ICAM-1 expression." (PMID 29088803, 2017). "We found that PC3 cells stably expressing CCN3 shRNA showed decreased tumor growth and metastasis." (PMID 29088803, 2017). "We found that E-cadherin and Twist expression correlated with CCN3 expression in tumor specimens." (PMID 29088803, 2017). "It is known that CCN3 promotes PCa bone metastasis by modulating the tumor–bone microenvironment." (PMID 29088803, 2017). "High expression of CCN3 was significantly correlated with vascular thrombosis and tumor dimension." (PMID 29061995, 2017). "In addition, the other CCN family members including CCN1, CCN2, and CCN3 also were higher in tumor than in normal." (PMID 26824419, 2016). "We found that tumor-secreted CCN3 could skew macrophages from an M1 to an M2 phenotype, which is likely to create a more immunosuppressive tumor microenvironment and thus impair anti-tumor responses." (PMID 24721786, 2014). "Finally, PCa-secreted CCN3 stimulated RAW264.7 cells and promoted angiogenesis in the chick chorioallantoic membrane assay (CAM), and increased tumor growth and tumor-associated angiogenesis in a PCa xenograft mouse model." (PMID 24721786, 2014). "Moreover, CCN3 expression, together with connexin 43, correlates positively with reduced tumour cell growth in choriocarcinomas and glioblastomas." (PMID 18789696, 2008). "Truncation of the CCN3 protein might occur under chromosomal rearrangements and mutagenic events that occur during tumor progression." (PMID 16504021, 2006). "Therefore, we speculated that the comparison of CCN3 expression in normal and tumor tissues requires further studies focusing on post-translational regulation rather than comparison of simple expression levels." (PMID 36737605, 2023). "In addition, CCN3 regulates cancer cell mobility, which correlates with tumor metastasis." (PMID 29088803, 2017). "Interestingly, the effects of recombinant CCN2 peptide on U-CH1 cells were more pronounced under normoxia than hypoxia, promoting increased expression of CCN1, CCN2, CCN3 and CCN5, the notochord-associated markers SOX5, SOX6, T, CD24, and FOXA1 as well as increased tumour-sphere formation." (PMID 25541962, 2014). "Moreover, CCN3 promotes PCa bone metastasis by modulating the tumor–bone microenvironment." (PMID 24721786, 2014). "However, the limited size (20 kb) of the insert DNA that was contained in the lambda recombinants, did not permit to establish whether MAV LTR sequences were present in the vicinity (at a genome scale) of the ccn3 gene in the DNA of all tumor cells." (PMID 16403231, 2006).
tumor (continued). "The concentrations of the growth factors and cytokines TGF-ß1 and VEGF, as well as the tumor-related proteins CCN1 and CCN3, were evaluated in cell culture supernatants of MG63 and HT1080 in response to indirect PRF treatment for 2 days." (PMID 38671725, 2024). "Results showed that the high value of regulatory potential between MFAP5 and some of its top predicted NOTCH1/WNT pathway target genes (CCND1, HES1, MYC, RBPJ, NOTCH1, CCN3, CTNNB1 and SOX17) in inferring signaling paths in tumour tissues." (PMID 36855786, 2023). "Increased expression of CCN1, CCN2, CCN3 and CCN4 is closely related with cell adhesion, proliferation and migration, and thus they can contribute directly to tumorigenesis, tumor development and metastases." (PMID 34940056, 2021). "In this study we show that BLR100 and BLR200, two CCN2-targeting, CCN3-derived peptides, can actively modify the PDAC microenvironment and increase tumor response to chemotherapy." (PMID 32294968, 2020). "In this study, we have provided evidence of tumor promoting effects of CCN3, which includes induction of epithelial-to-mesenchymal transition (EMT) and tumor metastasis." (PMID 29088803, 2017). "Collectively, these results show that CCN3, a PCa-secreted factor, increased M2 macrophage polarization, TAM-promoted angiogenesis and tumor growth in the PCa microenvironment in vivo." (PMID 24721786, 2014). "Also, we identified novel predicted tumor-suppressive ligands (SLIT3, DCN, CCN3, THBS1, INHA and INHBA), proteins (DNASE1L3, SULF1, PTEN, OAS1, and DAB2IP), and receptors (P2RX4, CDHR2, PTPRJ, and PTPRH) in MSC1 cells." (PMID 40564222, 2025). "Blocking various chemokines produced by tumor and stromal cells, such as monocyte chemoattractant protein-1 (MCP-1), prostaglandin E2 (PGE2), colony-stimulating factor 1, and CCN3, can inhibit the recruitment of TAMs to tumor sites, thereby suppressing tumor progression and preventing metastasis." (PMID 40304000, 2025). "Consistently, knockdown of CCN3 in PCa cells inhibits RAW264.7-promoted angiogenesis and tumor growth in mouse models, suggesting that CCN3 secreted by PCa cells regulates TAMs infiltration and function by modulating the FAK/Akt/NF-κB signaling pathway in macrophages." (PMID 38397187, 2024). "Our findings that peptides based on specific amino acid sequences of CCN3 are indeed able to inhibit fibrosis and angiogenesis confirm that CCN3 can antagonize CCN2, even in a tumor setting rich in CCN2, and supports the rationale for the development of such CCN3-based compounds for PDAC therapy." (PMID 32294968, 2020). "The NOV gene product, CCN3, has been reported in a diverse range of tumors to serve as a negative growth regulator, while acting as a tumor suppressor in Chronic Myelogenous Leukemia (CML)." (PMID 31014357, 2019). "The overexpression of CCN3 through lentiviral infection of MHCC97H cells in mice led to increased number of HSC with high expression of α-SMA, and the enhanced subcutaneous tumor growth was found in the MHCC97H-CCN3 group (0.74 ± 0.30 g vs. 1.43 ± 0.19 g p = 0.0308)." (PMID 31805888, 2019). "We also evaluated CCN3 mRNA expression levels in 48-paired HCC tumor tissue samples and in adjacent non-tumor liver tissue samples." (PMID 29061995, 2017). "Moreover, knockdown of CCN3 in PCa cells inhibited RAW264.7-promoted angiogenesis and tumor growth in vivo." (PMID 24721786, 2014). "In a different cohort of 122 human breast tumors and 32 normal breast specimens, the expression of CCN3 was found to be lower in tumor tissues when compared to normal specimens." (PMID 24551846, 2014). "In this study, we demonstrated that PCa-secreted CCN3, an ECM regulator, could increase macrophage infiltration, M2 macrophage polarization, and VEGF production in the tumor microenvironment." (PMID 24721786, 2014).
tumor (continued). "Related to its interaction with growth factors, the CCN3 VWC domain might participate in some aspects of cell development and tumour formation, perhaps by mediating its oligomerization." (PMID 18789696, 2008). "Altered expression of CCN3 in a variety of cancers may reflect maintenance of a normal homeostatic function of the cell of origin, or may indicate requirement of specific CCN proteins for maintaining the undifferentiated tumor state." (PMID 15361251, 2004). "In addition, induction of CCN1/Cyr61 and CCN5/WISP2 was also found in the CCA tumors, whereas CCN3/NOV and CCN6/WISP3 did not have obvious changes in both the nontumor and tumor samples from the CCA tissues." (PMID 27829832, 2016). "In one small study, CCN3 transcript levels did not correlate with clinical parameters such as age of the patient, hormone receptor and HER2 status, grade, stage, lymph node involvement or tumor size." (PMID 22427255, 2012).